IL6 (interleukin 6)
Diseases named in the same sentence as IL6 in open-access papers (continued):
Sharing a sentence is not in itself a finding about the gene and the disease.
anemia (continued). "CKD and inflammation were the main causes of anemia of known etiology as characterized by higher levels of hepcidin and IL-6." (PMID 34836070, 2021). "It has also been reported that aqueous extract of TC protects against inflammation associated anaemia by modulating hepcidin expression, IL-6 and other pro-inflammatory cytokine cascade." (PMID 34115763, 2021). "In this respect, anemia, chronic renal failure, and atrial fibrillation were the conditions independently associated with elevated IL-6 levels." (PMID 33535417, 2021). "In this study, patients with elevated IL-6 were more likely to present with anemia, and an elevated IL-6 was associated with increased rates of hospitalization for heart failure and mortality." (PMID 33535417, 2021). "The factors independently associated with the increase in IL-6 were anemia 3.513 (1.163–10.607) and renal failure 0.963 (0.936–0.991), p < 0.05." (PMID 33535417, 2021). "Some previous studies using mouse model or human cell lines reported that IL-6 is a central mediator of chronic inflammation that causes anemia in aged persons." (PMID 32095285, 2020). "The presence of proinflammatory cytokines (e.g., IL-6) increases hepcidin expression, likely placing older patients at higher risk of developing anaemia." (PMID 32665863, 2020). "This is consistent with the trends found for maternal anemia and higher IL-8 and IL-6, considering that maternal anemia can be associated with fetal anemia." (PMID 32765436, 2020). "In MCD, interleukin-6 (IL-6) plays an important role, which is considered to be closely associated with its clinical presentation, with symptoms such as fever, weight loss, anemia, and elevated C-reactive protein (CRP)." (PMID 32705358, 2020). "IL-6 implicated to cause constitutional symptoms and anemia in MCD through the production of inflammatory cytokines and hepatic hepcidin, respectively." (PMID 32399323, 2020). "Chronic inflammation is another of the factors causing anemia and IL-6 contributes to the inflammation and development of anemia through the iron regulatory hormone hepcidin, and the iron exporter ferroportin." (PMID 32765436, 2020). "When considering raw p-values < 0.05, maternal anemia was associated with higher spontaneous production of IL-8 and IL-6 in peripheral blood and lower production in cord blood of IFN-γ." (PMID 32765436, 2020). "Till now, a large number of reports suggest that IL-6 is associated with a range of diseases with an inflammatory background., such as bone metabolism, anemia of chronic diseases and multiple cancers." (PMID 32210363, 2020). "CD47 inhibition can cause anemia and infections are more common in patients treated with the IL-6 antibody tocilizumab." (PMID 32814713, 2020). "During inflammation, hepcidin is upregulated by IL-6 and is responsible for iron compartmentalization within cells, in turn causing anemia of inflammation." (PMID 32349426, 2020). "Studies also suggest that selenium is linked to anemia through the modulation of inflammation via the IL-6 pathway, the increased expression of heme-oxygenase 1 and oxidative stress." (PMID 31597392, 2019). "IL-6 is the main cause of developing anemia chronic inflammation and is expressed in excess at sites of inflammation." (PMID 31057960, 2019). "Another study confirmed that IL-6 production and developed anemia were linked by inhibition of iron metabolism and the formation of erythrocytes in the bone marrow." (PMID 31057960, 2019). "Anemia of inflammation is caused by high levels of IL-6 which induces hepcidin secretion by hepatocytes resulting in hypoferremia with increased iron accumulation in tissues, and impaired erythropoiesis." (PMID 30608934, 2019). "Cytokines like TNF-α blunts erythropoietin effect and IL-1, IL-6 and interferon-γ interfere with iron metabolism causing anemia." (PMID 31387568, 2019).
anemia (continued). "Microvascular density was strongly correlated with renal dysfunction over the whole range of urea levels, independent of the experimental model and other CKD-associated conditions such as anemia (hematocrit), weight loss, and inflammation (IL-6 levels)." (PMID 29593228, 2018). "High serum IL-6 levels in pancreatic cancer patients are associated with symptoms such as anemia, metastasis, fatigue and most important cachexia, which is a severe complication for many of these patients." (PMID 30038723, 2018). "IL6 has been shown to be an independent predictor of HF morbidity and mortality as well as implicated in the development of anemia of chronic disease in HF patients." (PMID 28388657, 2017). "We demonstrated that inhibition of the IL-6 signaling pathway by MR16-1 treatment resulted in significant recovery of iron-deficiency anemia and alleviation of cancer-related symptoms." (PMID 27068103, 2016). "We concluded that humoral, nonspecific immunity (phagocytic activity and oxidative burst), and IL-6 are influenced in patients with iron deficiency anemia." (PMID 27893677, 2016). "We concluded that humoral, nonspecific immunity (phagocytic activity and oxidative burst), and the IL-6 are influenced in patients with iron deficiency anemia." (PMID 27893677, 2016). "It has been ascertained that IL-6 is associated with a large number of diseases with inflammatory background, such as anemia of chronic diseases, angiogenesis acute-phase response, bone metabolism, cartilage metabolism, and multiple cancers." (PMID 28066415, 2016). "In our study, serum IL-6 levels were significantly lower in iron deficiency anemia patients than controls." (PMID 27893677, 2016). "In spite of the increased EPO blood levels, anemia persisted and was linked to low serum iron and transferrin levels, while serum interleukin (IL)-6 and high sensitivity C-reactive protein (hs-CRP) levels showed the absence of systemic inflammation." (PMID 25867633, 2015). "Another report showed that inflammation mediated by IL-6 impairs iron availability, leading to iron-deficiency anemia." (PMID 24587369, 2014). "We showed that IL-6 – hepcidin axis is active in anemia associated with HL, but that other IL-6-induced, hepcidin-independent mechanisms probably play a role." (PMID 25045461, 2014). "In another study, metastatic renal cell carcinoma patients with IL-6 levels > 10 pg/mL had an increased risk of anemia (OR 3.86 p = 0.003)." (PMID 24576354, 2014). "As IL-6 is thought to be an important cause of the anemia of inflammation by inducing hepcidin expression, we used SAA-1 measurements as an indicator of IL-6 activity." (PMID 24681760, 2014). "IL-6 also acts on changing lipid concentrations in blood and on inducing the production of hepcidin which causes iron-deficient anemia." (PMID 22046525, 2011). "Because IL-6 has been implicated in the development of anemia in systemic JIA, we assessed the degree of correlation between the erythropoiesis signature and serum levels of various cytokines, including IL-6." (PMID 20576155, 2010). "Pro-inflammatory cytokines, particularly IL-6, cause anemia of inflammation by inducing hepatocytes to produce hepcidin, an iron regulatory peptide." (PMID 18523547, 2008). "During tumor progression, elevated cytokines (e.g., interleukin-6) and oxidative stress impair erythropoiesis, increase erythrocyte fragility, induce functional iron deficiency, and disrupt energy metabolism, thereby promoting the development of anemia." (PMID 40357040, 2025). "Additionally, IL-6 upregulates hepcidin, impairing iron absorption and release, which leads to functional iron deficiency and further exacerbates anemia." (PMID 41179861, 2025). "For example, IL-6 blockade has been shown to improve anaemia of chronic disease, improve sleep and has been associated with both weight gain and an improvement in muscle mass, all of which will serve to improve general health, with similar effects likely for other TTs." (PMID 40568845, 2025).
anemia (continued). "Comprehensive evaluation in these physiologically relevant systems—including cytotoxic efficacy, persistence, cytokine secretion (e.g., IL-6), and safety (e.g., off-target effects, anemia, and bone loss)—is essential to substantiate the therapeutic potential suggested by our Jurkat data." (PMID 40977952, 2025). "Multicentric Castleman’s disease (MCD) is associated with interleukin (IL)-6 secreted by germinal center B cells, and excessive production of IL-6 induces various symptoms, including fever, weight loss, anemia, hypoalbuminemia, hypergammaglobulinemia, and increased acute phase protein." (PMID 39776937, 2024). "The primary underlying mechanism of this form of anemia has been proposed to be the increased synthesis of hepcidin during inflammation and subsequent dysregulation of iron homeostasis, which is predominantly mediated by interleukin-6." (PMID 39410600, 2024). "Furthermore, this study indicates that treatment with steroids and IL-6 inhibitors is associated with delayed onset of anemia, with a subsequent decrease both in the proportion of transfused patients and in the amount of transfusion per patient." (PMID 38594746, 2024). "Inflammatory cytokines, such as interleukin-6 (IL-6), interleukin-1 (IL-1), and interferons are signaling molecules that play a key role in the inflammatory response and have been implicated in the development of anemia." (PMID 38799419, 2024). "Furthermore, anemia, a hematological consequence of congenital ID, was associated with higher levels of the inflammatory cytokine interleukin-6 (IL-6) in the CB of neonates born in Tanzania." (PMID 39683596, 2024). "Several cases of PPGL in patients with elevated interleukin-6 (IL-6) levels have been reported; these patients often exhibit symptoms including fever of unknown origin, weight loss, anemia, thrombocytosis, and systemic inflammatory response syndrome." (PMID 38669419, 2024). "This suggests that the anti-tumor efficacy of combined IL-6/IL-6R inhibition and ICIs for cancer-associated anemia may be tumor-dependent." (PMID 37208766, 2023). "IL-6, a proinflammatory cytokine, has been associated with cancer-induced anemia." (PMID 37208766, 2023). "Since IL-6 regulates circulating hepcidin levels under tumor conditions, blocking IL-6 with monoclonal antibodies tocilizumab or siltuximab may be suitable for the management of cancer-associated anemia." (PMID 37208766, 2023). "The anemia might be associated with low plasma iron levels that negatively correlate with significantly higher IL-6 levels." (PMID 35422870, 2022). "Furthermore, our mechanistic in vitro studies indicate that Pi elevations induce hepatic production of IL6 and IL1β to increase hepcidin expression in hepatocytes, a potential causative link between hyperphosphatemia, anemia, and skeletal muscle dysfunction." (PMID 35302487, 2022). "Recently, an observational trial demonstrated that high IL-6 and hepcidin levels at baseline were related to low blood Hb and iron absorption in TB patients, which was reversed upon chemotherapy and resolution of TB-associated anemia of inflammation." (PMID 36014824, 2022). "Despite the known association of IL-6 with anemia and CRP levels in RA, only a limited number of small or post hoc studies have evaluated the impact of biologic or targeted synthetic disease-modifying anti-rheumatic drugs (bDMARDs or tsDMARDs) on Hb and CRP levels." (PMID 36544236, 2022). "On the one hand, IL-6 participates in T-cell differentiation, B-cell maturation, synthesis and the secretion of immunoglobulins and is one of the main cytokines underlying the anemia of chronic disease." (PMID 35620179, 2022). "The etiology of CKD-associated anemia is multifactorial and includes absolute iron deficiency and functional iron deficiency, with the latter caused by inflammatory cytokines including interleukin-6 (IL6) and interleukin-1β (IL1β)." (PMID 35302487, 2022).
anemia (continued). "The high level of IL‐6 causes antierythropoietic effect, changes the sensitivity of progenitor cells to Epo and promotes apoptosis of immature RBCs causing to development of anaemia." (PMID 34277984, 2021). "It is widely acknowledged that low grade inflammation and chronic disease is associated with anaemia and that several pro-inflammatory cytokines, such as IL-6 and tumor necrosis factor-α (TNF-α) could inhibit erythropoiesis and the actions of erythropoietin." (PMID 33781199, 2021). "Taken together, Ferritin, IL-6 and IL-10 could play significant roles in the inflammatory processes, severe anemia and pathologies associated with malaria." (PMID 35223394, 2021). "Our findings that IL-6 and hepcidin were associated with low hemoglobin concentrations support the hypothesized mechanism for the anemia of inflammation (AI) that is commonly observed in older adults." (PMID 33806205, 2021). "Furthermore, it has been demonstrated that cytokines such as IL-6 inhibit erythroid progenitor proliferation and impair iron supply to developing erythroid cells, resulting in anaemia associated with chronic inflammation." (PMID 33715142, 2021). "IL-6 further stimulates the synthesis of hepcidin by blocking iron absorption and macrophage iron recycling, resulting in iron deficiency and, in turn, anemia." (PMID 34822590, 2021). "Genetic polymorphisms of proinflammatory cytokine genes such as IL-6 might play a crucial role in anemia caused by chronic renal diseases." (PMID 32720970, 2020). "In cancer, several cytokines namely tumor necrosis factor -α (TNF-α), transforming growth factor -β (TGF-β), interleukin-1 (IL-1), IL-6 and interferon-γ interfere normal erythrocyte production by modulating iron metabolism and blunting erythropoietin effect thereby causing anemia." (PMID 31387568, 2019). "IL-6 upregulates the transcription of hepcidin, the iron regulatory protein, which leads to reduction in iron absorption and sequestration of iron by macrophages and enterocytes, limiting iron delivery to erythroblasts thus causing a functional anemia." (PMID 29385208, 2018). "The supposed mechanism of these markers may be that cells in UTUC with a poor prognosis may secrete inflammatory cytokines such as interleukin-6 that cause anemia and low serum sodium levels." (PMID 29195499, 2017). "Because pro-inflammatory cytokines, such as interleukin-6 (IL-6), also stimulate hepcidin production, sustained inflammation may increase hepcidin, resulting in iron deficiency and anemia." (PMID 28335426, 2017). "Our results suggest that overproduction of hepcidin by IL-6 signaling might be a major factor that leads to functionally iron-deficient cancer-related anemia in the LC-06-JCK model." (PMID 27068103, 2016). "Anemia is associated with lower handgrip strength in community-dwelling older persons even after adjustment for inflammatory markers such as C-reactive protein, interleukin-6, and tumor necrosis factor-α25." (PMID 27549351, 2016). "Furthermore, systemic features, including anemia and hypergammaglobulinemia, which are potentially associated with interleukin-6, are occasionally present." (PMID 25624890, 2015). "The authors conclude that anemia of chronic diseases is associated with high serum IL-6 and hepcidin levels, which supports the hypothesis that IL-6-driven hepcidin production mediates anemia in patients with IBD." (PMID 25646159, 2014). "Patients with myxoma may also present with Raynaud phenomenon, anemia, fever, weight loss, hypergammaglobulinemia, and an increased erythrocyte sedimentation rate due to the interleukin-6 release from the tumour cells." (PMID 24826252, 2012). "However, the causal relation of the induction of hepcidin by IL-6 and the development of anemia by sustaining elevated hepcidin levels has been shown by others in separate experiments." (PMID 21219610, 2011). "Hepcidin is an interleukin-6 (IL-6)-induced key modulator of inflammation-associated anemia." (PMID 21219610, 2011).
anemia (continued). "Clinical trials testing antibodies against IL-6 or its receptors have demonstrated its involvement in the pathogenesis of several autoimmune and inflammatory disorders and in the systemic inflammation and anemia associated to kidney failure and also in kidney allograft rejection." (PMID 40357502, 2025). "Anemia of inflammation is caused by the reduction in the lifespan of erythrocytes, impaired proliferation of red blood cells, and iron accumulation in the cells of the mononuclear phagocytic system via generation of proinflammatory cytokines, such as IL-6, causing hypoferremia." (PMID 37111212, 2023). "It has been stated that individuals with iron deficiency anemia may have decreased IgG levels, interleukin 6 (IL-6) and phagocytic activity, and that there is a significant positive correlation between serum level of iron and IL-6." (PMID 36986181, 2023). "While there is limited evidence for an erythropoietic role of vitamin D, the anti-inflammatory effects of vitamin D may reduce the risk of anemia via the suppression of interleukin-6 (IL-6) and a subsequent upregulation of the iron-regulating peptide, hepcidin." (PMID 33806205, 2021). "In addition, lymphopenia, elevated levels of the immune biomarkers C-reactive protein (CRP), interleukin 6 (IL-6), neopterin or ferritin, low levels of the iron transfer protein transferrin or testosterone deficiency and anemia were shown to be associated with an adverse outcome." (PMID 34677368, 2021). "Furthermore, more severe anaemia was associated with a higher IL-6 concentration." (PMID 33882880, 2021). "In addition to the joint phenotype, we observed signs of systemic inflammation in spondyloarthritic SKG mice, manifesting as pale BM (a sign of anemia), splenomegaly, an intestinal increase in expression of inflammatory genes, i.e., Il1, Il6, Il23, and Tnf, and weight loss." (PMID 31919358, 2020). "Furthermore, elevated levels of IL-6 and IL-8 may be associated with high parasite density and anemia, IL-8 with intrauterine growth restriction and IL-7 with absence of infection." (PMID 30930847, 2019). "Therefore IL-6 and ferritin level estimation may be workable test to differentiate the patients with iron deficiency anemia and anemia of chronic disease in RA." (PMID 31057960, 2019). "Therefore, the major cause of anemia observed in LC-06-JCK–bearing mice might be the increase in hepcidin production through IL-6 signaling leading to suppression of iron utilization." (PMID 27068103, 2016). "RA myxomas may remain asymptomatic or eventually cause constitutional signs and symptoms, including fever, weight loss, arthralgias, Raynaud phenomenon, anemia, hypergammaglobulinemia, and an increased erythrocyte sedimentation rate due to the production of interleukin-6." (PMID 22269461, 2012). "Anemia of chronic disease is a well-known extra-articular manifestation of RA, driven by pro-inflammatory cytokines like IL-6 that disrupt iron homeostasis and erythropoiesis." (PMID 41602254, 2026). "It is one of the main contributors to hypoferremia and anemia in inflammatory and oncological disorders that are mediated by the proinflammatory cytokine IL-6/STAT3 pathway." (PMID 40299525, 2025). "Due to its overlapping activity with respect to kala-azar, such as hemorrhages, anemia, hypoalbuminemia, and hyperglobulinemia, IL-6 was proposed to be the best explanatory cytokine for the complications of kala-azar." (PMID 40732663, 2025). "Results indicate that both drugs had insignificant difference in their effect on CKD pediatric anemia after 3 months of treatment except the effect on IL-6, GDF-15, TSAT, and GFR." (PMID 39910177, 2025). "Inflammatory cytokines are produced and exert their effects within the bowel microenvironment of IBD patients and, among them, Interleukin 6 (IL-6) induces the expression of hepcidin, encoded by the HAMP gene, contributing to the development of anemia." (PMID 41303636, 2025).